RNU6-830P (RNA, U6 small nuclear 830, pseudogene)
Gene: Small nuclear RNA gene on chromosome 1 (55,398,514 to 55,398,620, forward strand). Ensembl gene ENSG00000252162.
Homologues: Orthologues: chimpanzee U6 (97% identical), macaque U6 (93% identical), guinea pig U6 (62% identical). Paralogues in human: RNU6-166P (86% identical), RNU6-49P (86% identical), RNU6-820P (86% identical), RNU6-1091P (85% identical), RNU6-1152P (85% identical), RNU6-1158P (85% identical), RNU6-19P (85% identical), RNU6-31P (85% identical), RNU6-338P (85% identical), RNU6-35P (85% identical), RNU6-45P (85% identical), RNU6-589P (85% identical), and 1288 more.